MX1 (MX dynamin like GTPase 1)
Diseases named in the same sentence as MX1 in open-access papers (continued):
Sharing a sentence is not in itself a finding about the gene and the disease.
infection (continued). "We found that phosphorylation of STAT1 and STAT2 in A549 cells pre-treated with IL-36γ was inhibited at each post-infection point in time, while no significant changes in Mx1, PKR, IAV-Ca07 NP, and M1 protein were observed." (PMID 33193319, 2020). "This suggests that lncR 8 negatively regulates Mx1 and IFITM1 during HCV replication and infection." (PMID 31200545, 2019). "Levels of mRNAs for IFNβ1 and IFN response gene proteins Mx1, a GTPase induced by type I and type III IFNs38, and IFN-induced protein with tetratricopeptide repeats (IFIT)-1 were upregulated after infection with both YFV and ZIKV with the greatest response induced by YFV." (PMID 31289325, 2019). "Additionally, rNDV infection rate and ISG expression after Rux treatment showed a significant negative correlation (Oasl2: rs = −0.826, p < 0.01, Oas1b: rs = −0.720, p < 0.01, Mx1: rs = −0.543, p < 0.01)." (PMID 29882780, 2018). "Of the interferon regulatory factor (IRF) genes annotated in KEGG, expression of IRF7 was significantly upregulated, and interestingly, all downstream transcriptional targets of IRF9 annotated in KEGG (MX1, OAS genes, ADAR, and PML) were consistently upregulated during acute infection." (PMID 30150281, 2018). "To test this hypothesis, we examined the induction of Mx1, a well-characterized ISG product, during HSV-1 ICP0-null mutant infection by confocal microscopy." (PMID 29309427, 2018). "To compare the viruses' abilities to limit the establishment of an antiviral state, we infected equine cells (multiplicity of infection [MOI], 0.1) with each of the viruses and monitored the expression of two ISGs (ISG15 and MX1) by Western blotting at different times postinfection." (PMID 29237841, 2018). "Infection of PK15-cells with Vp447∆c or with Vp447 did not induce MX1 expression, but the protein was easily detectable upon infection with a Vp447 Npro deletion mutant." (PMID 28290554, 2017). "Infection of Irf3-/- mice confirmed an impairment in Mx1 and Ifit1 but not Tnf induction suggesting that IRF3 is critically involved in K. pneumoniae-elicited type I IFN production in vivo." (PMID 29112952, 2017). "On the other hand, PRRSV could inhibit IFN-mediated JAK-STAT signaling pathways to interrupt ISG transcription; for example, ISG15, ISG56, CCL2, MX1, OAS2, and RNaseL of PAMs were significantly downregulated after infection with the PRRSV strain VR2385." (PMID 27182980, 2016). "In addition, expression of two key ISG, Mx1 and OASL, was also examined by quantitative real time PCR during the ATMUV infection." (PMID 27449021, 2016). "Both MX1 and SAMHD1 expression were positively correlated with severity of CNS disease, consistent with a runaway immune response that, in acute phase infection, might be protective, but at later stages becomes damaging." (PMID 26936683, 2016). "Neither pre-infection CXCL10 nor MX1 transcript levels correlated with overall early plasma viral load." (PMID 27902344, 2016). "Twenty four host proteins (17 in the cytosol and seven in the nucleus) are up-regulated ≥1.5-fold by T3D infection but not by T1L infection, and four of these proteins (Mx1, ISG15, IFIT1, and STAT1) are up-regulated >3.5-fold by T3D." (PMID 25905045, 2015). "However, mammalian influenza viruses strongly up-regulated the expression of Mx1 and OAS1 which was likely to be a reflection of the presence of viable but infected cells at 6 h of infection." (PMID 26642934, 2015). "This study examined the mechanism underlying this phenomenon by measuring the expression of antiviral genes—tumor necrosis factor alpha (TNF-α) and GTPase myxovirus resistance 1 (MX1)—in G6PD-knockdown cells upon human coronavirus 229E (HCoV-229E) and enterovirus 71 (EV71) infection." (PMID 26694452, 2015). "In cells pre-treated with IFN-λ1 and then infected, MX1 mRNA increased between 18 and 48 h post-infection, although not as much as OAS1." (PMID 26411318, 2015).
infection (continued). "To further confirm the role of NF-κB in the virus-induced upregulation of the TNF-α and MX1 genes, we treated A549 cells with BAY 11-7085, a specific NF-κB inhibitor, and examined the temporal change in the expression of antiviral genes after infection." (PMID 26694452, 2015). "One possible reason for this discrepancy is that IFN-alpha in plasma becomes undetectable by ELISA in the chronic phase of the infection and is therefore less sensitive for determining the interferon response than measuring ISG like MX1 as in our work or ISG15." (PMID 26554913, 2015). "Components of interferon pathway and innate immunity (IFI44L, IFITM3, MX1, IRF7, OAS2, STAT2, etc.)are significantly upregulated in the acute phase of infection, while the expression levels of genes involved in translational elongation and protein biosynthesis are decreased." (PMID 26070066, 2015). "The results show that while IFNα mRNA gradually increased following infection and peaking at 24 hpi, Mx1 or PKR expression was not induced at any of the time points examined (3−48 hpi)." (PMID 25885006, 2015). "We therefore examined gene expression for several important interferon-related genes (IFNα2, IFNα4, IFNβ, IFNαβR, IFNγ, IFNγR, Irf3, Irf7, Mx1, Oas1, IFITM1, IFITM2), along with inflammasome-related genes IL-1β and NLRP3, and chemokines CCL5, CCL7, and CCL12 at d1 post-infection." (PMID 26110868, 2015). "As reflected by differences in respective protein levels, numerous members of this pathway were up-regulated by T3D infection but not by T1L infection, and Mx1 and IFIT3 were down-regulated by UV-T3D treatment." (PMID 25905045, 2015). "Moreover, many genes exhibited different levels of expression of the various isoforms under infection with one PRRSV strain vs. the other (PARP14, SOCS1, IFIT1, MX1, IFOTM1, RNASEL, PIKSCD and TLR3)." (PMID 24643046, 2014). "On the other hand, no significant change in the induction of OAS-2 and Mx1 was observed in these cells at late time points post infection." (PMID 24391501, 2014). "By 24 h of infection, however, expression of all four anti-viral genes and IFN-β and IL-6 was clearly up-regulated (p<0.05) in all three cell types; BEAS-2B cells displayed the highest expression of IRF-7, STING, Mx1 and IL-6." (PMID 25313647, 2014). "Interestingly, at early time point post infection, activation of STAT1 signaling promoted expression of OAS-2 and Mx1." (PMID 24391501, 2014). "Other IFN-responsive genes such as Mx1 were also significantly increased on day 2 post-infection whereas Ifnα was not induced by Y. pestis." (PMID 22911267, 2012). "On day 5 post infection, both viruses induced the expressions of RIG-I, Mx1 and OAS." (PMID 21826229, 2011). "In the brains infected with Pigeon04, mRNA expression levels of Mx1, OAS, IL6, IL1β and CCL5 were at least 17 fold higher than those of respective genes in the infected lungs on day 5 post infection when this virus almost similarly replicated in the lungs and brains." (PMID 21826229, 2011). "Similar to IFNβ mRNA induction, IRF7, Mx1 and ISG15 mRNA levels could also be detected as early as 3 hrs post-infection, with peak levels observed at 16 hrs post-infection." (PMID 22028657, 2011). "Thus, after infection with SC35M-ΔNS1, the extent of Mx1 gene expression in lungs of mice with defective receptors for IFN-α/β, IFN-λ or both correlated inversely with virus titers." (PMID 18787692, 2008). "For example, hypermethylation within MX1 may have no impact upon a calf that is not actively responding to an infection." (PMID 40316897, 2025). "The infection with viral strains that were only defective in the expression of MHC immune evasion genes US2, US3, US6, and US11 still showed some reduction in the steady-state levels of ISGs Mx1 and ISG15, but also showed slightly elevated levels of IFIT3, compared to the wt-control virus." (PMID 40143353, 2025).
infection (continued). "In addition to their distinct Mx1 response, plasma SOD activity increased in suboptimal-fat diet bats in response to infection, which could increase their capacity to prevent the formation of reactive species, suggesting a role of systemic redox balance." (PMID 39968620, 2025). "Treatment of MDBK and bovine white blood cells with IFN-α, as well as infection with bovine herpes virus 1, and bovine rotavirus upregulated Mx1 gene expression whereas, infection of bovine endometrial cells with ncp BVDV (Pe515nc strain) reduced/inhibited Mx1 and Mx2 gene expression." (PMID 39224597, 2024). "By contrast, the overexpression of circYthdc2 or Linear-FLAG-Ythdc2-170aa both could significantly inhibit the expression levels of interferon IFN1, inflammatory cytokines (TNF-α), and antiviral genes such as myxovirus resistance protein 1 (Mx1), ISG15, and Viperin after SCRV infection." (PMID 38361078, 2024). "Specifically, infection of MAGI1-null ECs with IAV upregulates expression of signal transducer and activator of transcription 1 (STAT1), interferon b1 (IFNb1), myxovirus resistance protein 1 (MX1) and 2′-5′-oligoadenylate synthetase 2 (OAS2), and activate STAT5." (PMID 36082118, 2022). "Furthermore, Mx1 reduces the HSV-1 replication in human fibroblasts, and CXCL10-null mice that are infected with HSV-1 and -2 have reduced numbers of NK and CD8+ T cells at the site of the infection and increased rates of viral replication." (PMID 36423126, 2022). "Finally, experimental infection of normal cells of human origin by LS-L289A, APMV-4, and rAPMV-4 resulted into stronger upregulation of genes involved in antiviral response, as measure by the expression levels of IFNβ and MX-1." (PMID 35937459, 2022). "Additionally, IL-27 stimulation prior to infection led to significantly increased Mx1 transcription in our study, but it did not significantly increase Oas1-3 transcripts." (PMID 36678402, 2022). "Infection-induced gene expression levels of inflammatory cytokines such as Il6 and Tnf, type I (Ifna4 and Ifnb), and type III IFNs (Ifnl2/3) as well as ISGs such as Mx1, Isg15, and Stat1 peaked simultaneously with peak viral loads on day 2 p.i. in lungs and upper airways." (PMID 36129445, 2022). "Thus, we next measured expression of several ISGs, including Isg15, Ifit1 and Mx1, over the same time course in BMDMs in addition to RAW 264.7 macrophages and observed significant induction of these genes 4h post-infection with higher induction at 8h in both cell types." (PMID 34473814, 2021). "At the transcriptome level, the high expression levels of viral sensors MDA5 (IFIH1), R1G-1 (DDX58), and ISGS (ISG15, Mx1, Mx2, RSAD2, IFIT3, and IFIT5) and transcription factors like IRF-7 and STAT-1 that induce ISG expression were found in lymphocytes during virulent PPRV infection." (PMID 34631844, 2021). "Since the upregulation of MX1 was most prominent in naïve SC at the later timepoints of infection, we next questioned whether IFN-I signaling could be protective against ZIKV in SC if triggered prior to infection." (PMID 34079533, 2021). "However, the overall differences in MX1 expression over the five days post-infection were not statistically different (p-value = 0.12)." (PMID 34919598, 2021). "Importantly, these cell types also do not upregulate detectable levels of the IFN-dependent ISG Mx1 in response to ΔPB1-Cre infection, indicating that interferon is likely not secreted by any cell type." (PMID 32790753, 2020). "Likewise, phosphorylation of STAT1 and STAT2 in 16HBE cells pre-treated with IL-36γ was mildly inhibited at 12 h after IAV-Ca07 infection, while no significant changes in Mx1, PKR, IAV-Ca07 NP, and M1 protein were observed." (PMID 33193319, 2020).
infection (continued). "Both infected and uninfected cells upregulate Mx1 in response to ΔHA-Cre, suggesting that amplified virus replication is required to induce IFN production in vivo and any genes upregulated in ΔPB1-Cre infected cells, including genes designated as ISGs, are likely due to direct infection." (PMID 32790753, 2020). "We show that the expression of the interferon-stimulated proteins MX1, IFIT1, IFIT3 and ISG15, as well as expression of defense response proteins DDX58, STAT1, OAS3, EIF2AK2 and SAMHD1 was significantly up-regulated in these cells upon infection with either virus." (PMID 30959732, 2019). "Our data highlighting the relevance of IFNAR signaling on hepatocytes during CVB3 infection are in accordance with a previous report in which upon infection with a hepatotropic influenza A virus strain MX1 induction in hepatocytes was also independent of IFNLR triggering." (PMID 30075026, 2018). "Similarly, overexpression of Mx1 significantly reduced viral titers in JH4 cells at 72 hours post infection, but did not affect viral replication during the first 48 hours." (PMID 28418930, 2017). "However YFP expression in macrophages was not specific to infection, as it was widespread also in naive (and specific pathogen-free) Mx1-cre x ROSA26-YFP mice." (PMID 27223694, 2016). "AEC1s made no detectable Mx1 response to infection or to poly(I:C)." (PMID 27223694, 2016). "Similarly, the cecal expression of Mx1 was largely upregulated after PR8 infection in the WT mice, but not in the Ifnar1-/- mice, and as anticipated the level of induction of Mx1 tended to be lower overall in the Ifnar1-/- mice compared to WT mice." (PMID 27149619, 2016). "Pre-infection MX1 RNA levels did not correlate with overall plasma viral load." (PMID 27902344, 2016). "Since functional analysis of genes upregulated at the presymptomatic (3 dpi) stage of WNV-ND showed that some of genes (MX1 and STAT1) have a dual immune-neural functionality (i.e., being pleiotropic), we next sought to determine whether the number of such genes increased as infection progressed." (PMID 33599611, 2021). "Therefore, we hypothesized that IFN might be induced during early infection, as indicated by the subsequent enhanced production of ISGs because increased expression of a variety of ISGs, such as OSAL, MX1, IFIT5, ISG12-2, RSAD2, IFI35, protein kinase R (PKR), and IFI27L2, was found in this study." (PMID 24168272, 2013). "Protein lysates collected after interferon pre-treatment, but prior to infection, showed decreased levels of representative ISGs IFIT1 and MX1 upon CPSF6 knock-out, though not to the same extent as observed upon IFNAR1 knock-out." (PMID 41385587, 2025). "The infection increased IFN-β, IFN-λ1, Mx1, OAS1, PKR, and RIG-I but it did not alter IFN-α and IFN-λ3 expressions." (PMID 40565228, 2025). "Protein lysates collected after interferon pre-treatment, but prior to infection, showed decreased levels of a representative ISG, MX1, upon CPSF6 knock-out, though not to the same extent as observed upon IFNAR1 knock-out." (PMID 39678349, 2024). "Similar to the lab-adapted strains, we observed six ISG-related DAPs (IFIT1, IFIT2, IFIT3, OAS3, ISG15, and MX1) significantly upregulated compared to MOCK infected UNOs, upon infection with clinical isolates of PeV-A3, but not PeV-A1." (PMID 38514653, 2024). "The conditioned medium of KpOMV-stimulated macrophages, unlike direct vesicle stimulation, induced Mx1 expression in these cells and reduced IAV replication in subsequent infection experiments." (PMID 36978183, 2023). "Herein, we observed no significant change in the mRNA expression profiles of the antiviral ISGs MX1 and IFITM1 during secondary H3N2 infection nor HRV-A16 re-infection as compared to their respective single infections in hNECs." (PMID 37190061, 2023).
infection (continued). "We also validated the significant elevation in the baseline protein expression of MX1 and IFITM1 after 14 days of prolonged primary HRV infection (even without sequential infection of hNECs)." (PMID 37190061, 2023). "The data indicated that single treatment with Pte or Pin during EV-D68 infection did not influence intrinsic innate immune status, as there were no observable changes in the expression of IFN-α, IFN-β, IFIT1, or MX1." (PMID 36845118, 2023). "Infection of MDCK Npro cells did not increase IFNβ, ISG56 or Mx1 RNAs, independently of the presence of Dot1L inhibitor (bottom), which coincided with the inability of these cells to produce IFN and ISG." (PMID 29352168, 2018). "In neither immunized macaques from E1 (available pre-infection samples: n=14) nor those from E2 (n=11) did relative expression of FAM26F, MX1 and CXCL10 before infection correlate with the extent of early viral replication." (PMID 27902344, 2016). "At the early time post-infection, lamina propria cells that readily respond to exogenous type I IFN did not contain detectable levels of Mx1 in wild-type or Ifnlr1-/-, suggesting that type I IFN production was low." (PMID 25849543, 2015). "In contrast, Mx1 protein was not visible in HCVcc-infected iHLCs cultures treated with the IL28RA nAb, strongly implicating endogenous IFN-λs produced during infection as the main stimulus driving ISG induction in this hepatic system." (PMID 25826356, 2015). "Interestingly, a similar level of induction of total STAT1, P-STAT1 (Y701), and MX1 was observed even in uninfected SUIT-2 (but not in MIA PaCa-2) in response to siMETTL3 treatment (“SUIT-2, mock-infection, siSCR” vs “SUIT-2, mock-infection, siMETTL3”)." (PMID 40214229, 2025). "At the earlier time points post-infection, we did not observe any overlap with down-regulated mRNAs; however, 27 up-regulated mRNAs were common to all early treatment groups, including TLR3, IFIT5, IFIH1 (MDA5), MX1, RSAD2 (viperin), CMPK2, SOCS1, and SCNN1D." (PMID 38675946, 2024). "Therefore, we investigated expression of IL-15 and ISGs, such as APOBEC3G, ISG15, ISG20, MX1, MX2, and RSAD2, after infection with R5-tropic, non-opsonized (HIV) and complement-opsonized (HIV-C) HIV-1 strains (BaL and YU-2)." (PMID 34634939, 2021). "Furthermore, the frequencies of the MX1+ ACE2− and SOCS3+ ACE2− cells were not affected by infection, but were significantly affected by age, and were highly accumulated in the lung tissues of both healthy and infected old RMs." (PMID 34471088, 2021). "Indeed, Mx1 was not upregulated in RRV-infected NOD.IFNAR1−/− mice, indicating that their lymphocyte activation from day 5 post infection occurred independently of type 1 interferon secretion." (PMID 27405244, 2016). "In the present study, we observed that several ISGs with known or proposed anti-CCHFV activity, i.e., Mx1, ISG15 and ISG20 or not defined for CCHFV like IFIT1, IFIT3, IFITM3, IFI16, and OAS3 were upregulated in the acute phase CCHFV patient samples as well as in the cell-infection model." (PMID 35437144, 2022). "Interestingly, analysis of ISG expression indicates that TRIM26 OE cells had no significant increase in MX1 and ISG15 expression after infection, in contrast to WT VK2 and TRIM26 KO cells, suggesting that TRIM26 may have a direct regulatory role for these ISGs." (PMID 33419081, 2021).